CD34 (CD34 molecule)
Diseases named in the same sentence as CD34 in open-access papers (continued):
Sharing a sentence is not in itself a finding about the gene and the disease.
glioblastoma (35 papers, 2010 to 2025). The most malignant astrocytic tumor (WHO grade IV). "As a highly prevalent human β-herpesvirus, HCMV establishes lifelong latency in CD34+ myeloid progenitor cells and has been implicated as an oncomodulatory virus in various cancers, including glioblastoma multiforme, breast, prostate, colorectal, and ovarian cancer (OC)." (PMID 41463341, 2025). "CD34 staining were also associated with hypoxia-induced angiogenesis and may play a role in glioblastoma hemorrhage." (PMID 31968004, 2020). "Using CD34-positive cells from human glioblastoma, we conducted an endothelial sprouting assay alongside a mouse aortic ring sprouting assay to evaluate the angiogenic capacity of DPEP1 in the presence of cilastatin." (PMID 40319462, 2025). "Applying CD34 staining to glioblastoma samples enables the estimation of microvessel density and aids in identifying outlier survival cases." (PMID 40892951, 2025). "Neovessels with a glomeruloid aspect, associated with intense positivity for CD34 or CD105 in endothelial cells, were observed, characteristic of glioblastomas." (PMID 38928515, 2024). "All other studies assessing CD31, VE-cadherin, CD34, VEGFR2, and vWF determined that mRNA expression of these markers was associated with the transdifferentiation of glioblastoma cells to endothelial cells." (PMID 36823554, 2023). "The results of this review suggest that expression of endothelial markers CD31 and/or CD34 distinguishes tumour to endothelial transdifferentiation from VM in glioblastoma." (PMID 36823554, 2023). "The collective results of the studies included in this review suggest that identification of VM in glioblastoma tissue can be achieved by IHC using either CD31 or CD34 labelling in combination with PAS staining of the basement membrane of the vessel structure." (PMID 36823554, 2023). "A decrease in CD34+ vessel density in recurrent glioblastoma has been previously reported, with one study suggesting that this is due to a reduction in total tumour tissue present after standard treatment." (PMID 37568738, 2023). "Four types of CD34-labeled microvessel formations in glioblastomas have been detected based on different vascular niche pathologic structures: microvascular sprouting, vascular cluster, vascular garland, and glomeruloid vascular proliferation." (PMID 35562993, 2022). "To compare the phenotype of tumor-associated HSPCs with canonical HSPC subsets, we obtained single cell transcriptomes from magnetically enriched CD34+CD45+ IDH wt glioblastoma cells (n = 660 cells) derived from a fresh surgical specimen." (PMID 34162860, 2021). "In glioblastoma samples, CD34 expression was observed in the cytoplasm of tumor vascular endothelial cells." (PMID 28771552, 2017). "While the immunohistochemical labeling of some glioblastomas for CD34 is recognized, this phenomenon is generally foreign to infiltrating astrocytomas of lower grade and to neoplasms of the oligodendroglioma group." (PMID 27812792, 2017). "We are also aware that CD34 occasionally stains glioblastoma tumour cells and in such situations tumour cells will be stained red by the red chromagen and will thus be excluded from analysis." (PMID 24252243, 2013). "A total of 4974 CD34+ cells in 971 vessels were examined in the 86 glioblastomas, including 3852 CD34+ cells in 768 vessels from tumors showing EGFR amplification or gain of chromosome 7." (PMID 22298889, 2012). "The number of CD34+ endothelial cells with extra EGFR copies was similar in glioblastomas with chromosome 7 gain or EGFR amplification and the smaller subset lacking such abnormalities (p=0.8, Fisher Exact Test)." (PMID 22298889, 2012). "These limitations are especially prominent in the analysis of glioblastoma CD34-stained images." (PMID 40892951, 2025). "This study focuses on IHC images obtained using CD34 antibodies to stain glioblastoma tissues." (PMID 40892951, 2025).
glioblastoma (continued). "In the normal brain, CD34 is not detectable; however, it is commonly positive in low grade glioneuronal tumours and malformations associated with epilepsy and in a subset of glioblastomas." (PMID 37568909, 2023). "In addition, we noticed an expansion of a CD45+CD34− immune cell population within the organoid cultures, indicating that a subset of HSPCs are differentiating in the presence of patient-derived glioblastoma cells." (PMID 34162860, 2021). "CD34 expression is also candidate as a prognostic biomarker in glioblastoma to identify survival and could also be predictive for efficacy of bevacizumab." (PMID 31968004, 2020). "However, we feel the CD34 staining by glioblastomas cells is usually just focal so that it should be possible in most cases to find interpretable areas in the slide." (PMID 24252243, 2013). "Thus, angiogenesis is considered as a pathologic hallmark of GB, leading to VEGF activation, an angiogenic growth factor that promotes glioblastoma proliferation and CD34 activation, a transmembrane glycoprotein involved in the process of newly-forming tumour vessels." (PMID 34298658, 2021). "However, the tissue targeting protocol of that study may be biased, as for 4 glioblastoma patients, authors reported less than 6 detected vessels with CD34 endothelial marker." (PMID 30808879, 2019). "Formalin-fixed paraffin-embedded tissue from 35 matched pairs of primary and recurrent glioblastoma was immunohistochemically labelled for PSMA and CD34 and stained with periodic acid–Schiff (PAS)." (PMID 37568738, 2023). "Compared to IDH1-mutant tumours, glioblastomas showed significantly higher expression of EGFR, MEOX2, and CD34 and significantly lower positivity for SOX11." (PMID 37568909, 2023). "A fraction of stem-like cells isolated from glioblastomas have been shown to express a number of endothelial cell markers including CD31, CD34, CD105, VE-cadherin, von Willebrand factor (vWF), and VEGF receptor 2 (VEGFR2)." (PMID 36823554, 2023). "This would support the results of a previous study, which showed a reduction in the number of both CD34+ and PSMA+ vessels in recurrent compared to matched primary glioblastoma samples." (PMID 37568738, 2023). "Identification of glioblastoma-derived endothelial cells in tissue samples also commonly used CD31 and CD34 as markers." (PMID 36823554, 2023). "Immunohistochemical labelling for CD34 and staining with PAS were used to identify endothelial, VM, and mosaic vessels in glioblastoma tissue sections." (PMID 37568738, 2023). "Labelling for the endothelial cell marker CD34 through immunohistochemistry (IHC) and staining with PAS is the most frequently used method of identifying VM vessels in glioblastoma tissue." (PMID 37568738, 2023). "To test if HSPCs can be identified in glioblastoma tissues by classical immunofluorescence, we determined the status of CD34 and CD45 in paraffin embedded formalin fixed glioblastoma tissues (n = 4 patients)." (PMID 34162860, 2021). "To more directly address the capacity of glioblastoma cells to contribute to the vascular endothelium, we performed double labeling (Immunofluorescence/FISH) for the endothelial marker CD34 and EGFR gene locus." (PMID 22298889, 2012). "Most vessels were CD34+/PAS+ endothelial vessels, and as such there was also a statistically significant decrease in endothelial vessel density in recurrent (41.34 vessels/mm2) compared to primary (86.98 vessels/mm2) glioblastomas (z = −3.759, p < 0.001)." (PMID 37568738, 2023). "CAFs were also noted to be in close proximity to cells expressing glioblastoma stem cell (GSC) marker CD44 and were enriched in the perivascular niche where GSCs reside based on their proximity to endothelial cells expressing CD34 or CDH5." (PMID 36856115, 2023).
glioblastoma (continued). "In addition to completely CD34− vessels, we observed vessels that were partially CD34+ in a subset of both primary and recurrent glioblastomas." (PMID 37568738, 2023). "Notably, high DPEP1 expression correlates with poor survival in glioblastoma patients across multiple cohorts, while CD34 expression showed no impact on patient survival." (PMID 40319462, 2025). "Vascular areas of tumour tissue that were PSMA+ were also CD34+ on the subsequent section, indicating that PSMA is expressed by endothelial vessels, not VM, in glioblastoma." (PMID 37568738, 2023). "Glioblastoma stem cells present several biomarkers used for identification, such as CD133, nestin, musashi-1, CXCR4, CD15, CD34, CD44, SOX2, L1CAM, and A2B5, however, neither being exclusively characteristic for GSCs." (PMID 35562993, 2022). "Additionally, epidermal growth factor receptor (EGFR) gene amplification could not be identified in CD34+ endothelial cells within the vascular linings of glioblastoma tissue, further supporting the unlikely contribution of glioblastoma cells to tumor vessel formation." (PMID 32375250, 2020). "We examined 40 primary brain tumours (30 glioblastomas and 10 oligodendroglial tumours) with our new technique, namely double-labelling immunohistochemistry for MGMT and a "cocktail" of non-tumour antigens (CD34, CD45 and CD68)." (PMID 24252243, 2013).
coronary artery disease (34 papers, 2010 to 2024). "Specifically, reduced exercise-induced mobilisation of CD34+CXCR4+ HPCs is associated with increased CVD in patients with coronary artery disease." (PMID 35222269, 2022). "Autologous CD34-positive cell therapy for ischemic heart disease is associated with increased LVEF, exercise time, neovascularization, decreased angina, nitroglycerine use, heart failure, and mortality." (PMID 34394711, 2021). "The relevance of its increased transcription in CD34+ cells in CAD patients is underscored by the association of a polymorphisms in GATA2 with familial early onset coronary artery disease." (PMID 20565948, 2010). "A previous study found that the expression of a retinoic acid signature reduced the capacity of circulating CD34+ cells from coronary artery disease patients to migrate to ischemic tissues." (PMID 35672803, 2022). "It has been reported that clopidogrel enhances atorvastatin-induced mobilization of EPCs as demonstrated by the presence of CD34+/CD133+/KDR + cells in patients with coronary artery disease." (PMID 33113567, 2021). "The therapeutic benefits of administering CD34+ cells in patients with ischemic heart disease are believed to be attributable to the angiogenic capacity of EPCs." (PMID 29760742, 2018). "In our study, patients with a higher SYNTAX score, which is an indicative of higher atherosclerotic burden and more severe ischemic heart disease, had a lower number of CD34+KDR+ and CD34+CD38− cells." (PMID 28819363, 2017). "In coronary artery disease, fewer CD34+KDR+ cells are seen while in heart failure or atherosclerotic disease progression more CD34+KDR+ cells occur in circulation." (PMID 28278173, 2017). "Previous studies have shown an increase in the circulating concentration of population CD34+CD45− cells in patients with established coronary artery disease (CAD) and peripheral artery disease." (PMID 26237060, 2013). "Intracoronary infusion of autologous CD133+/CD34+ BMMNCs reduces infarct size in patient with coronary heart disease and post infarction cardiosclerosis." (PMID 23983717, 2013). "In this work, we therefore used CD133+/CD34+ BMMNCs in cardiac tissue remodeling in patients with coronary heart diseases and postinfarction cardiosclerosis." (PMID 23983717, 2013). "Knowledge is still scarce about the transcriptional programs used by CD34+ cells from peripheral blood, and how these are affected in coronary artery disease (CAD) patients." (PMID 20565948, 2010). "Great attention has recently been given to selected subsets of circulating CD34+ cells in patients with ischemic heart disease, as these cell populations might include those involved directly or indirectly in vascular repair." (PMID 22985188, 2012). "Several studies describe a lower number of CD34+/KDR+ cells in patients with coronary artery disease (CAD); these low numbers seem to be inversely correlated with cardiovascular risk factors; moreover, this EPC decrease has been directly linked to CAD and to precede future cardiovascular events." (PMID 22214418, 2012). "Therefore, in our study, we analysed the correlation between the diseased coronary arteries and the frequency of CD34/45+ BM-CPCs in peripheral blood (PB) in patients with ischemic heart disease (IHD)." (PMID 22118372, 2011). "Moreover, smoking is associated with depletion of CD34+ and CD133+ endothelial progenitor cells in patients with coronary artery disease." (PMID 22118372, 2011). "CD34+CPCs could be inversely modulated by cardioinflammatory status, and a low CD34+CPC number was associated with an increased risk of death in subjects with coronary artery disease." (PMID 35885020, 2022). "Moreover, our group has discovered that the in vitro migratory activity of CD34+ MNCs positively correlated with cardiovascular death, independently from other predictive factors, such as age, coronary artery disease, serum C-reactive protein, and glomerular filtration rate [82•]." (PMID 33651185, 2021).
coronary artery disease (continued). "Indeed, studies have reported that HDL cholesterol levels correlate with the number of circulating CD34+/KDR+ EPCs in subjects with coronary artery disease, and with the number of CD34+/CD133+ EPCs in hypercholesterolemic subjects and in obese non diabetic women." (PMID 29866130, 2018). "These experiments examined the relationship between the separate insults of IR and mechanical injury on vasomotor function and CD133+/CD34+/VEGFR2+ EPC in healthy subjects and patients under investigation for coronary artery disease." (PMID 24719774, 2014). "Previous studies have demonstrated, that the mobilization and functional activity of CD34/45+ and CD133/45+ BM-CPCs significantly increased after intracoronary infusion of BMCs in patients with ischemic heart disease." (PMID 22534049, 2012). "Previous studies demonstrated, that the mobilization and functional activity of CD34/45+ and CD133/45+ BM-CPCs significantly increased after an intracoronary infusion of BMCs in patients with ischemic heart disease." (PMID 22118372, 2011). "We may further develop novel pro-angiogenesis treatment for ischemic heart disease by mediating VEGF secretion and targeting CD34+ M_SH cells." (PMID 37147443, 2023). "After receiving an intracoronary infusion of CD34+ cells, patients with ischemia and nonobstructive coronary artery disease had higher coronary flow reserves, less severe angina, and better quality of life." (PMID 36660500, 2022). "have shown that intracoronary administration of autologous CD34+ cell therapy effectively alleviates angina and endothelial dysfunction in non-obstructive coronary artery disease, highlighting the potential of this therapeutic approach to address these complex cardiovascular conditions." (PMID 39749331, 2024). "The percentage of CD34+ cells within harvested bone marrow and CD34+ cell mobility in an SDF-1 gradient was compared with and without autologous serum in age-matched healthy volunteers free from any symptomatic coronary artery disease (N = 10) and patients participating in our trial (N = 6)." (PMID 23737803, 2013). "Furthermore, our phase I and II clinical trials previously demonstrated that intracoronary transfusion of CD34 + cells improved left ventricular function in patients with diffuse coronary artery disease (CAD) and noncandidates for coronary artery intervention." (PMID 39568005, 2024). "Pre-surgical CD34+/CD144+ numbers are decreased in CABG patients, compared to valvular patients with absence of coronary disease." (PMID 22214418, 2012).
HCMV infection (34 papers, 2005 to 2025). "CD34+ HPCs are isolated from bone marrow, cord blood, or fetal liver with a high degree of purity and are susceptible to HCMV infection." (PMID 40736257, 2025). "This cell-type-dependent regulation of EGFR supports a possible requirement for EGFR signaling during CMV infection of CD34+ HPCs for the establishment of latency, and loss of EGFR or PI3K signaling enhances reactivation potential during infection." (PMID 30127257, 2018). "By screening HCMV-encoded miRNAs at various stages of experimental latent HCMV infection in CD34+ HPCs and Kasumi-3 cells, the present study demonstrated that miR-UL148D robustly accumulates during the establishment of experimental latency." (PMID 27824944, 2016). "It is possible that HCMV infection of CD34 cells could induce cell differentiation and loss of primitive properties including reduction of CD34 expression." (PMID 15673469, 2005). "HCMV infection of CD34+ hematopoietic progenitors specifically alters differentiation through virus/host interactions." (PMID 40736257, 2025). "Epidermal growth factor receptor (EGFR) is an entry receptor for HCMV infection of CD34+ HPCs, and signaling through this pathway contributes to the establishment and maintenance of latency." (PMID 40736257, 2025). "In this culture system, HCMV infection of CD34+ cells is characterized by very low levels of viral transcripts compared to replication-permissive cell types." (PMID 40736257, 2025). "Studying HCMV infection of CD34+ HPCs in vitro is also challenging, given the difficulty of maintaining progenitors in an undifferentiated state in culture." (PMID 40668819, 2025). "Herein, we utilized a proximity-dependent biotinylating enzyme (TurboID) to characterize the US28 interactome when expressed in isolation, and during both latent (CD34+ hematopoietic progenitor cells) and lytic (fibroblasts) HCMV infection." (PMID 37782657, 2023). "According to a recent study, a latent HCMV infection of CD34+ HPCs induced the secretion of TGF-β, which is responsible for virus-mediated myelosuppression." (PMID 35214602, 2022). "MiR-UL148D is highly expressed during the late stages of experimental latent HCMV infection in CD34+ progenitor cells and in Kasumi-3 cells." (PMID 35214602, 2022). "The level of the STAT1 gene has been shown to increase in CD34+HPC cells of B7-H4-/- mice with human cytomegalovirus infection." (PMID 36514159, 2022). "It has been observed that miR-US5-1 and miR-UL112-3p are expressed in CD34+ hematopoietic progenitor cells (HPCs) during the early stages of HCMV infection." (PMID 35214602, 2022). "The bone marrow is an important tissue site in the etiology of HCMV infection as it is a known resident site of CD34+ cells which have been shown to carry the latent virus in natural infection." (PMID 36558866, 2022). "We have previously shown that experimental latent HCMV infection of CD34+ progenitor cells alters the cellular secretome resulting in the upregulation of chemokines CCL8, CCL2 and secretion of TGF-β and cellular IL-10 (cIL-10)." (PMID 33912186, 2021). "EGFR signaling is also suggested to play a role in the establishment of latent HCMV infection in CD34+ HPCs by regulating several key early steps." (PMID 34299120, 2021). "In the context of latency, HCMV infection in CD34+ HPCs sustained a low basal level of EGFR activity." (PMID 34299120, 2021). "Utilisation of the monocyte, a derivative of CD34+ progenitor cells, to export the latent HCMV infection from the bone marrow to the periphery is one possible strategy for the virus to employ in order to reach an appropriate environment for virus replication." (PMID 33912186, 2021). "In the context of HCMV infection, we have previously demonstrated that secreted factors from latently infected CD34+ cells promoted the migration of CD14+ monocytes and resting CD4+ T cells." (PMID 33912186, 2021).